GOLGA8O (golgin A8 family member O)
Tractability: No criterion of Open Targets' tractability assessment is met for any kind of drug.
Gene: Protein-coding gene on chromosome 15 (32,441,914 to 32,455,634, reverse strand). Ensembl gene ENSG00000206127.
Gene Ontology:
Molecular function: protein binding
Biological process: Golgi organization
Cellular component: cis-Golgi network; Golgi cis cisterna; Golgi cisterna membrane; Golgi apparatus
Genetic constraint (gnomAD): Loss-of-function variants: 1 observed, 5.87 expected, observed/expected ratio (o/e) 0.17, 90% interval 0.06 to 0.81. That is too few expected variants to judge how well the gene tolerates losing a copy. Missense variants: 15 observed, 35.65 expected, observed/expected ratio (o/e) 0.42, 90% interval 0.28 to 0.65. Synonymous variants: 4 observed, 9.32 expected, observed/expected ratio (o/e) 0.43, 90% interval 0.21 to 0.98.
Homologues: Orthologues: chimpanzee GOLGA8S (89% identical), mouse Golga2 (44% identical), dog GOLGA2 (43% identical), tropical clawed frog golga2 (33% identical), zebrafish golga2 (30% identical), Drosophila melanogaster GM130 (22% identical), Caenorhabditis elegans golg-2 (19% identical), rat Golga2l1 (5% identical). Paralogues in human: GOLGA8N (99% identical), GOLGA8Q (99% identical), GOLGA8R (98% identical), GOLGA8M (92% identical), GOLGA8H (91% identical), GOLGA8J (91% identical), GOLGA8K (90% identical), GOLGA8T (90% identical), GOLGA8S (84% identical), GOLGA8F (80% identical), GOLGA8G (80% identical), GOLGA8A (66% identical), and 6 more.